SP1 (Sp1 transcription factor)
Diseases named in the same sentence as SP1 in open-access papers (continued):
Sharing a sentence is not in itself a finding about the gene and the disease.
bladder cancer (25 papers, 2005 to 2023). "It was also reported that curcumin, a yellow substance of the polyphenols superfamily, attenuated bladder cancer progression partially by suppressing Sp-1 activity." (PMID 35293283, 2022). "Morin decreases CDK2, CDK4, cyclin D1, and cyclin E via modulation of the p21/WAF1 pathway, suppressing c-Jun N-terminal kinase (JNK) and AKT phosphorylation, and preventing MMP-9 expression by repressing NF-κB, SP-1, and AP-1 in EJ bladder cancer cells." (PMID 33996570, 2021). "For example, our recent study found that SP1 was overexpressed in bladder cancer and functioned as an oncogene to promote cell migration and invasion." (PMID 32432112, 2020). "We found that nimbolide treatment reduced the activation of the transcription factors NF-κB, AP-1, and Sp-1 in bladder cancer cells." (PMID 31391858, 2019). "Here, we further reveal that Sp1 bound directly to the mmp‐2 promoter and increased its transcription, promoting bladder cancer cell invasion." (PMID 28846829, 2017). "ROS and hydrogen peroxide (H2O2) play a role in downregulation of Sp1, Sp3 and Sp4 in pancreatic and bladder cancer cells and treatment of RKO cells with BA for 36 h induced ROS as determined by FACS analysis using the fluorescent ROS scavenger H2DCFDA." (PMID 21864401, 2011). "Therefore, the different levels of the Akt/SP1 signaling axis in bladder cancer cell lines may contribute to different FTO expression levels." (PMID 33634966, 2021). "NAC has been reported to revert fucoidan-induced apoptosis and downregulations of telomerase reverse transcriptase (TERT), c-myc, Sp1 transcription factor, and AKT expressions in bladder cancer cells." (PMID 35624705, 2022). "During migration and invasion of bladder cancer cells, MMP-9 regulation is controlled via activation of the transcription factors NF-κB, Sp-1, and AP-1." (PMID 31391858, 2019). "In this study, we reveal that Ras up-regulates RbAp46 expression in human breast and bladder cancer cells as well as in mouse fibroblast 7–4 cells, and the binding of RbAp46 with HDAC and Sp1 represses RECK promoter activation via the Sp1 site." (PMID 25885317, 2015). "Arsenic trioxide also induced caspase-dependent cleavage of Sp3 and Sp4 in bladder cancer cells and retinoid (CD437)-induced Sp1 degradation was also caspase-dependent in EL-4 cells." (PMID 23110215, 2012). "Previous studies showed that BA-induced downregulation of Sp1, Sp3 and Sp4 was proteasome-dependent in LNCaP cells but proteasome-independent in KU7 bladder cancer cells." (PMID 21864401, 2011). "Determination of the level of XPC gene 5' regulatory region DNA co-precipitated with the transcription factors CREB1 and Sp1 by IP in both untreated and VPA-treated HTB4 and HTB9 bladder cancer cells a." (PMID 21507255, 2011). "By binding to E2F1 and Sp1, respectively, BIR2 and BIR3 domains initiate E2F1/Sp1-positive-feedback-loop-dependent transcription of miR-203, inhibiting Src protein translation, which leads to further MMP2-cleaved activation and BC (Bladder Cancer) invasion." (PMID 33138314, 2020). "Furthermore, nimbolide impaired the migration and invasion of bladder cancer cells by reducing MMP-9 expression, which was mediated by transcriptional suppression of the transcription factors NF-κB, AP-1, and Sp-1." (PMID 31391858, 2019). "Previous studies demonstrated high specificity for knockdown of Sp1, Sp3 and Sp4 by RNAi in RD rhabdomyosarcoma and KU7 bladder cancer cells, whereas in other cell lines, knockdown of an individual Sp protein also decreased expression of one or both of the other gene products." (PMID 26967243, 2016). "For example, knockdown of Sp1 (siSp1) or Sp3 (siSp3) in 253JB-V bladder cancer cells decreased expression of Sp4 protein, whereas siSp4 did not affect levels of Sp3 or Sp1 proteins." (PMID 26967243, 2016).
neuroblastoma (25 papers, 2007 to 2026). Neuroblastoma (NB) is the most common solid, extracranial childhood tumor. "Overexpression of mice α-synuclein or the A53T mutant in mice neuroblastoma cells lines increases sp1 expression which, through the binding with the promoter, enhances MAOA expression." (PMID 36768321, 2023). "We previously reported that serum deprivation triggers EGFR-dependent activation of the PI3K/Akt pathway in neuroblastoma N2a cells, which is crucial for the Sp1-dependent transcription of P2rx7 gene." (PMID 36589747, 2022). "Specificity protein 1 (Sp1) is a transcription factor that plays a crucial role in the control of P2rx7 gene expression in neuroblastoma." (PMID 36589747, 2022). "Subsequently, SP1 reduces Aβ-induced neurotoxicity, neuronal apoptosis, and ROS-mediated oxidative damage in human neuroblastoma cells (SH-SY5Y)." (PMID 34164050, 2020). "Altogether, these results reveal that serum deprivation induces activation of PI3K/Akt pathway that results in Sp1-induced expression of P2rx7 gene in neuroblastoma cells." (PMID 26687764, 2015). "Next, we faced the question of how PKCζ is regulating Sp1-dependent P2rx7 gene expression in neuroblastoma cells." (PMID 26687764, 2015). "Noticeable, GF109203X treatment also increased Sp1 protein levels in SH-SY5Y human neuroblastoma cells, effect that was completely abolished by PI3K inhibition." (PMID 26687764, 2015). "Serum withdrawal triggers EGFR-dependent activation of the PI3-kinase/Akt pathway in neuroblastoma cells, resulting in the phosphorylation of the Sp1 transcription factor and the induction of P2X7R expression, which promotes cell proliferation in the absence of trophic support." (PMID 37776398, 2024). "Moreover, miR-519a-3p was discovered to hinder MPP+-evoked apoptosis and inflammation in neuroblastoma cells via the NEAT1/miR-519a-3p/SP1 axis." (PMID 35350655, 2022). "We previously identified Sp1 as the main nuclear factor involved in controlling P2rx7 gene expression in N2a neuroblastoma cells and here, blocking Sp1-dependent transcription with mithramycin A significantly reduced but did not abolish the expression of P2RX7 in BCI-treated cells." (PMID 36589747, 2022). "Likewise, in neuroblastoma Neuro2a cells, it was recently demonstrated that the transcriptional activator Sp1 directly binds the synapsin I promoter, activating its transcription, and that its activity is directly modulated by the neural master regulator REST." (PMID 27223470, 2016). "Moreover, inhibition of PI3K also decreased Sp1 protein levels in SH-SY5Y human neuroblastoma cells, pointing to PI3K as the main regulator of Sp1 transcriptional activity in neuroblastoma cells." (PMID 26687764, 2015). "In studies carried out in neuroblastoma cell lines, it was observed that Sp1 increases the expression of synapsin I (SYN I), while REST prevents the binding of Sp1, decreasing SYN I." (PMID 38542313, 2024). "This was given emphasis when Siaw and colleagues proposed that ALK activation in neuroblastoma can inhibit DLG2 transcription via ERK1/2 and specificity protein 1 (SP1) signalling, thus impairing DLG2-induced differentiation." (PMID 34769149, 2021). "Tolfenamic acid inhibited the transcription factor Sp1, which reduced the transcription of APP and BACE1 in Pb-exposed human neuroblastoma SH-SY5Y cells and decreased Aβ accumulation in APP transgenic mice." (PMID 32517647, 2020). "Sp1 and NF-kB transcription factor binding sites are present on NGB promoter and their binding is demonstrated in neuroblastoma cell lines." (PMID 27313512, 2016). "We cloned the previously used Sp1 and PrP10 targets into these vectors as well, and tested the SpCas9-induced repair of GFP in N2a neuroblastoma cells." (PMID 27630115, 2016). "For example, Sp1 was found to affect the chromatin accessibility of CD151 and P2X7 receptor promoters in liver cancer cells 34 and neuroblastoma cells 35, respectively." (PMID 26763486, 2016).
neuroblastoma (continued). "Treatment with LY294002 and API-1 significantly reduced nuclear Sp1 levels, suggesting that Sp1 is a downstream effector of PI3K/Akt pathway in neuroblastoma cells." (PMID 26687764, 2015). "Interestingly, in human neuroblastoma cells Sp1 has been reported to form a repression complex with MYCN and MIZ1, and that Sp1 cell depletion has been found to induce the expression of p75NTR and TrkA." (PMID 34360553, 2021). "Previously we identified specificity protein 1 (Sp1) as the main factor involved in the transcriptional regulation of P2rx7 gene, reporting that serum withdrawal triggers the expression of P2X7R in Neuro-2a (N2a) neuroblastoma cell line." (PMID 26687764, 2015). "Sp1 role in the regulation of complex I subunits, was demonstrated by the ability of the Sp1/DNA binding inhibitor, mithramycin, to inhibit the transcription of NDUFV1 and NDUFV2, in neuroblastoma cells." (PMID 17786189, 2007). "In addition, we verified that RELA was not involved in CD271 expression in neuroblastoma or normal epithelial cell lines, which differed from a previous study suggesting that Sp1 is important for CD271 transcription in neuroblastoma cells." (PMID 36273237, 2022). "Moreover, EGFR inhibition also reduced Akt phosphorylation induced by serum deprivation, indicating that EGFR activation is necessary to trigger PI3K/Akt signaling pathway and, consequently, to induce Sp1-dependent upregulation of P2X7R in neuroblastoma cells lacking trophic support." (PMID 26687764, 2015). "Altogether, these data indicate that activation of EGFR enhanced the expression of P2X7R in neuroblastoma cells lacking trophic support, being PI3K/Akt/PKCζ signaling pathway and Sp1 mediating this pro-survival outcome." (PMID 26687764, 2015).
liver cancer (24 papers, 2012 to 2025). An epithelial or non-epithelial malignant neoplasm that arises from the liver. "We also found in Kaplan–Meier survival curves that a high expression of either PNPase, SP1 or NFY subunit A (NFYA) is associated with a poor prognosis in liver cancer." (PMID 36232701, 2022). "Consequently, the regulation of the formation of the SP1/NFY complex could be the underlying cause for the rise in the PNPT1 expression associated with a poor outcome in liver cancer patients." (PMID 36232701, 2022). "Plicamycin treatment also decreases GSDME expression in a concentrate-dependent manner in both HeLa and human liver cancer cell line Huh7 cells, consistent with the Sp1 knockdown results." (PMID 38238307, 2024). "Mechanistically, ZRANB1 stabilizes and binds SP1 through deubiquitination, which promotes liver cancer progression." (PMID 35875077, 2022). "Subsequently, USP39 was found to stabilize the SP1 expression to induce malignant biological behaviors of liver cancer." (PMID 36582601, 2022). "Cancer literatures proved that miR-22-3p targets SP1, inhibits the expression of downstream genes CCND1 and BCL2, thereby inhibiting the growth of liver cancer cells, and the low expression of miR-22-3p is associated with metastatic liver cancer." (PMID 35011220, 2022). "We found that HBx increased C4BPα through activating transcription factor Sp1 in protection of liver cancer cells from complement attack in a nude mouse model." (PMID 27050367, 2016). "Together, these results illustrate that Sp1 positively controls TIAM2S transcription and that Sp1‐mediated transcriptional activation is essential for TIAM2S ectopic expression in liver cancer cells." (PMID 26763486, 2016). "RNA interference (RNAi) studies showed that among several lncRNAs expressed in HepG2, SNU-449 and SK-Hep-1 cells, highly upregulated in liver cancer (HULC) was regulated not only by Sp1 but also Sp3 and Sp4 in the three cell lines." (PMID 26317792, 2015). "Regulation of HULC by Sp1, Sp3 and Sp4 in liver cancer cells was investigated by RNAi with oligonucleotides that targeted the individual Sp transcription factors." (PMID 26317792, 2015). "By analysing ChIP-seq data for SP1, SP2, and SP5 in the liver cancer cell line HepG2 (downed from ENCODE), we found direct binding of SP1, SP2, and SP5 to the promoters of most SRTs near TSSs, which exhibited strong H3K27ac occupancy and open chromatin accessibility." (PMID 38185659, 2024). "Further studies are necessary to determine whether, under liver cancer pathological conditions, the accumulation of PNPase is a consequence of SP1/NFY complex formation or just a matter of expression levels of the individual transcription factors." (PMID 36232701, 2022). "In addition, SP1 was highly upregulated in liver cancer, and the expression of SP1 was positively correlated with BRPF1 expression." (PMID 34285329, 2021). "Thus, we conclude that HBx up-regulates C4BPα through activating transcription factor Sp1 in protection of liver cancer cells from complement attack." (PMID 27050367, 2016). "In summary, this study demonstrates that Sp1 and other Sp transcription factors are important for liver cancer cell growth, migration, survival, invasion and epithelial-mesenchymal-transition, and we demonstrate that HULC and other lncRNAs are Sp-regulated genes in HCC." (PMID 26317792, 2015). "Therefore, USP39 can target Sp1 to promote liver cancer cell proliferation." (PMID 35875077, 2022). "Therefore, the objective of this study was to investigate whether Sp1‐mediated transcriptional activation contributes to the ectopic expression of TIAM2S in liver cancer cells." (PMID 26763486, 2016). "In liver cancer cells, metformin administration decreased HULC by inhibiting the expression of specificity protein 1 (sp1), a transcription factor." (PMID 41226441, 2025). "A positive correlation between SP1 and SOX4 was observed through TCGA liver cancer data (n = 361, p = 4.9e−23, R = 0.46)." (PMID 35924788, 2022).
liver cancer (continued). "Immunohistochemistry analyses confirmed that the expression levels of PKCι, Sp1, and TMBIM6 were correlated with one another in samples from human breast, prostate, and liver cancer patients." (PMID 31336725, 2019). "Here, we found that an orphan nuclear NR2E3 maintains AHR expression, and forms an active transcriptional complex with transcription factor Sp1 and coactivator GRIP1 in MCF-7 human breast and HepG2 liver cancer cell lines." (PMID 28878246, 2017). "Compared with normal liver cells (i.e., HepaRG), Sp1 expression was significantly increased 4.4‐ and 3.7‐fold in PLC/PRF/5 (P < 0.001) and HepG2 (P = 0.001) liver cancer cells." (PMID 26763486, 2016). "Using Sp1 knockdown as a model, HCC cells were transfected with siHULC or siSp1 and their effects on transwell migration and invasion of the three liver cancer cell lines were determined." (PMID 26317792, 2015). "Using the GeneMANIA prediction server and HPA, we discovered that SP1 could interact with MAT2A, and the complex may translocate into the nuclei in liver cancer." (PMID 37240447, 2023). "We also analyzed the correlation between NACO3, SP1 and TERT mRNA expression in liver cancer patients in the GEO database (GEO: GSE10143), the mRNA level of SP1 was a positive correlation with the NCOA3 (R2 = 0.7367, p < 0.0001) and TERT (R2 = 0.0.401, p < 0.0001)." (PMID 33239622, 2020). "Additionally, the immunohistochemistry data demonstrated the expression pattern of the PKCι, Sp1, and TMBIM6 is well matched in breast, prostate, and liver cancer clinical tissue samples." (PMID 31336725, 2019). "Moreover, other transcription factors such as SP1 and CREB14, 15 have been shown to have a role in regulating the basal expression of TIGAR in liver cancer cell lines." (PMID 26247727, 2015). "The relative expression of Sp transcription factors in tumors from HCC patients or in liver cancer cell lines has not been reported; however, there is indirect evidence that Sp1 and Sp-regulated genes are negative prognostic factors." (PMID 26317792, 2015).
multiple myeloma (22 papers, 2011 to 2024). "SP1 is a transcriptional regulator that is associated with dysregulated cell cycle arrest in multiple myeloma." (PMID 26694754, 2015). "On the other hand, miR29 can inhibit multiple myeloma cell proliferation via SP1 activation synergizing with bortezomib, causing a potent demethylating effect and inhibiting osteoclastosis and important pathogenetic effects in multiple myeloma patients." (PMID 26262875, 2015). "In multiple myeloma, the inhibition of HDACs was associated with the down-regulation of Sp1, indicating that the effects of HDAC expression might be mediated by Sp1." (PMID 32585896, 2020). "The recovery percentages of IP/INPUT, indicating the binding of c-Myc to the Sp1 was exposure time-dependently reduced on the CD26 promoter of myeloma cells on treatment with each HDACi." (PMID 38284882, 2024). "Sp1 is a transcription factor that is expressed in several solid tumor cells as well as in myeloma cells." (PMID 38284882, 2024). "Collectively, these results confirm that HDACi plays crucial roles not only through its anti-myeloma activity but by sensitizing CD26neg myeloma cells to CD26mAb via c-Myc/Sp1-mediated CD26 induction, thereby augmenting its cytotoxicity." (PMID 38284882, 2024). "In multiple myeloma, SP1 and P300 form a complex that regulates the transcription of IQGAP1 and thus promotes tumor cell proliferation." (PMID 37599359, 2023). "By reducing Sp1 expression, another study showed reduced cell proliferation and increased apoptosis in multiple myeloma cells." (PMID 36840005, 2023). "Recently, LicA was shown to be an Sp1 antagonist, with strong inhibitory effects on viability and proliferation of myeloma cells." (PMID 36840005, 2023). "A similar mechanism was observed in multiple myeloma cells as well where SP1/EP300 complex promoted proliferation of cancer cells through modulating the transcription of IQGAP1." (PMID 35242497, 2022). "We report here a novel c-Myc/miR-23b/Sp1 feed-forward loop with a critical role in multiple myeloma (MM) and Waldenstrom's macroglobulinemia (WM) cell growth and survival." (PMID 26771806, 2016). "Multiple myeloma is a well-known hematologic malignancy that is regulated by Sp1 transactivation and the NF-κB pathway, and downregulation of Sp1 and RelA induces tumor regression." (PMID 27545642, 2016). "A wide range of concentrations of mithramycin A (10 nM–1 μM) have been used to inhibit the transcriptional factor activity of Sp1 in various types of cells, including human bronchial epithelial cells, multiple myeloma cells, and mouse endothelial cells." (PMID 21779326, 2011). "Finally, on the basis of these observations, we further examined the interaction between c-Myc and Sp1 on the CD26 promoter of myeloma cells in the presence or absence or HDACi." (PMID 38284882, 2024). "Fulciniti also found that in multiple myeloma cells the miR23b/SP1/c-myc feed-forward loop could activate caspase-3 thus promoting cell proliferation." (PMID 34905435, 2021). "Therefore, we postulated that the interaction between c-Myc and Sp1 on the CD26 promoter of myeloma cells may be one of mechanisms which regulate the activity of the CD26 promoter gene to induce CD26 expression in myeloma cells." (PMID 38284882, 2024). "The fact that it has been shown that bortezomib also leads to transcriptional downregulation of Sp1 (another transcription factor involved in the regulation of KIT39) as well as Notch in multiple myeloma and acute lymphocytic leukemia strengthens our hypothesis." (PMID 32198455, 2020). "Thus MYC-dependent miR-23b repression in myeloma cells may promote activation of oncogenic Sp1-mediated signaling, representing the first feed-forward loop with critical growth and survival role in myeloma." (PMID 26771806, 2016).